LAG3 (lymphocyte activating 3)
Diseases named in the same sentence as LAG3 in open-access papers (continued):
Sharing a sentence is not in itself a finding about the gene and the disease.
tumor (continued). "Interestingly, single inhibition of either LAG-3 or PD-1 alone does not result in improved control of chronic infection or tumor growth, pointing out the complex interactions among inhibitory receptors, whereby dual blockade synergistically reverses the exhausted phenotype." (PMID 28073373, 2017). "IPI-549 or PD-L1 single or dual treatments did not affect PD-1, CTLA-4, TIGIT, LAG-3, or TIM-3 expression in tumor-infiltrating CD4+ T-cells in HNSCC tumor-bearing mice." (PMID 41431358, 2026). "The number of T cells within the tumor area had little effect on the overall survival time, and not CD4 + or CD8 + cells, but the density of LAG3 + T cells showed a strong correlation with prognosis (43.0 vs 9.1 months, p < 0.001)." (PMID 40411616, 2025). "This resulted in increased immune regulator molecules such as CTLA4, PDL1, Tim3, VISTA, LAG3, CD38, CD80, CD86, MHC Class II, and PD-L1 being presented on the surface of trogocytic tumor cells compared to non-trogocytic tumor cells." (PMID 40440354, 2025). "Tumor-infiltrating iNKT cells, being the most glycolytic, are rather PD1-negative and LAG3-negative, suggesting that subverted PD1+ and/or LAG3+ iNKT cells exhibit a rather low glycolytic capacity, but a high mitochondrial dependency." (PMID 41562072, 2025). "Compared to non-IBC, HER2+ IBC tumour cells engaged CD8+ T cells through the MIF–CD74 ligand–receptor axis, while CD8+ T cells specifically upregulated immune checkpoint molecules LAG3 and TIGIT." (PMID 40624675, 2025). "Tumor-infiltrating lymphocytes (TILs) showed a high expression of TIM-3 and TIGIT in both SCC and ADENO, while LAG-3-positive TILs were absent in ADENO and present in 46% of SCC." (PMID 40647508, 2025). "Single cell RNAseq analysis of tumor infiltrating CD8 T cells shows positive correlation of CTLA-4, TIM-3, LAG-3, TIGIT, GITR, 4-1BB, and OX40 with PD-1 but negative correlation of KLRG1 with PD-1." (PMID 39832302, 2025). "In numerous nonclinical models, blocking both LAG-3 and PD-1 improved T cell function, aiding in viral and parasitic infection clearance, and enhancing CD8 + T cell-mediated anti-tumor activity." (PMID 40234667, 2025). "They found that co-inhibitory receptors PD-1, TIM-3, LAG-3, and TIGIT were expressed at relatively low levels on B cells in both tumor and non-tumor tissues, with some indication of increased expression on B cells isolated from tumor tissue." (PMID 41008839, 2025). "Although we couldn’t observe a significant change of CD19 + LAG-3 + IgD + cells for tDLNs and tumor samples in neither of the models throughout the weeks, we detected a decrease of the population in the spleen of 4T1 tumor-bearing mice 21 days after tumor inoculation." (PMID 38773133, 2024). "Tumor exposure alone or with TIGIT blockade did not change the frequency of NK cells expressing inhibitory receptors TIM-3, NKG2A, LAG-3, PD-1, or CD96 compared to isotype control or unexposed NK cells." (PMID 37345049, 2023). "Tumor infiltrating lymphocytes with high co‐inhibitory receptor expression such as CTLA4, PD‐1, and LAG3 have been regarded as functionally exhausted rather than activated." (PMID 37789961, 2023). "As expected, there were very few PD-1 + Lag3 + T cells infiltrating tumors in the KPC GEMM, consistent with a lack of tumor antigen specificity and a distinction from the KPC2a model." (PMID 36472588, 2023). "In contrast, we did not see the differential expression of LAG3, PDCD1, and HAVCR2 genes in the blood of any patient groups, suggesting differences between the tumor and blood circulation immune microenvironments." (PMID 37762493, 2023). "However, persistent ISG hubs in tumors, as shown in a recent MMRd CRC tumor atlas, may ultimately drive immunosuppression because of the negative feedback that upregulates immune checkpoints and co-inhibitory factors such as PD1/PDL1, Lag3/MHC-II, Tim3/LGALS9, and IDO1 through IFN overstimulation." (PMID 37492581, 2023).
tumor (continued). "In the present investigation, while PDL1 and PDL2 expression in the tumor group was lower than that in the normal group, the expression of TIGIT, CTLA4, LAG3, and PD1 in the tumor group was higher than that in the normal group." (PMID 37266661, 2023). "While, the score of LAG3 in IM was observed to be higher in patients with higher T-stages (T3/T4) (P = 0.027), the absence of TLS in CRC tissues (P = 0.014), and larger tumor size (P = 0.052)." (PMID 36765348, 2023). "We analyzed the correlation between CLDN18.2 and other immune checkpoint inhibitors in the tumor core; unfortunately, we did not observe any correlation with PD-1, PD-L1, CTLA-4, LAG-3, or TIM-3." (PMID 35811317, 2022). "It was not clear how the expression and infiltration by TIM3+ LAG3+ CTLA4+ and PD1+ cells affect the tumor microenvironment in HGSC." (PMID 36359346, 2022). "As for MH T cells, OT-1 CD8+ T cells with and without edited expression of PD-1, LAG-3, and TIM-3 showed comparable cytotoxicity against tumor cells." (PMID 35328630, 2022). "Otherwise, the mRNA expression of LAG3, CTLA4, PD-1, PD-L1, and HAVCR2, tightly related to tumor immunosuppression or tolerance, were not significant differences in ACC with CENPFhigh, compared with CENPFlow (all p > 0.05)." (PMID 35123514, 2022). "LAG-3 is frequently co-expressed with PD-1 on activated CD4- and CD8-positive tumor-infiltrating T-cells, and is known to be a negative regulator of T-cell function." (PMID 36289918, 2022). "The data demonstrate that the simultaneous genetic ablation of PD-1, LAG-3, and TIM-3 expression induced a more sustained anti-tumor activity compared to non-edited T cells resulting in reduced tumor growth as well as increased survival." (PMID 36077354, 2022). "Since Kaede Red+ Tregs in the dLN and spleen expressed significantly less CD25 and CD39 than LAG-3+ Tregs in the tumor, our data was consistent with the egress of LAG-3− Tregs, rather than simply the downregulation of LAG-3 by Tregs upon or after egress." (PMID 35472220, 2022). "Blocking LAG-3 alone did not restore T cell exhaustion; however, the combination of LAG-3/PD-1 blockade resulted in reduced tumor volume." (PMID 34025438, 2021). "Using the stratification cut-off points as in the assessment of tumor response, the patients with high post-TACE concentrations of LAG-3 and PD-L1 were not correlated with a significantly but a tendency towards impaired OS." (PMID 34691076, 2021). "Nonetheless, LAG-3 knockout CAR-T cells showed no superiority in terms of the anti-tumor response and the reduction in tumor burden compared to the conventional CAR-T cells." (PMID 34321099, 2021). "Especially interesting in this respect is the co-expression of PD-1, LAG-3, and TIM-3 on CD8+ TILs, as these are shown to phenotypically identify tumor-reactive CD8+ lymphocytes, regardless of antigen specificity." (PMID 34298622, 2021). "Treatment with this anti-PD-L1 secreting CAR-T cell led to a 50% decrease in T cell exhaustion markers (LAG-3, TIM-3 and PD-1) compared to treatment with a non-secreting CAR-T cell and a three times profounder reduction in tumor mass." (PMID 32325898, 2020). "Using immunohistochemistry, we were able to show that the tumor cells, and not the stroma, are responsible for the aberrantly expression of MHC-II, a ligand of the immune-check point protein LAG-3." (PMID 32641473, 2020). "We also found that RFA increased the infiltration of CD8+PD-1+ T cells in distant non-RFA tumor on day 3 after RFA treatment, whereas at the same time upregulated the expression of PD-1 and LAG3, the critical immune checkpoint regulators in the T cells." (PMID 32719347, 2020). "In this study, in addition to the expression of LAG‐3 protein on tumor‐infiltrating lymphocytes, ectopic expression of LAG‐3 was also detected via immunohistochemistry in tumor tissues, but it was not expressed in benign lung tissue." (PMID 32077528, 2020).
tumor (continued). "Immune checkpoint (PD-1, LAG-3 and TIM-3)-positive CD4+ and CD8+ T cells cannot exert an anti-tumor effect and are regarded as nonfunctional or exhausted subsets." (PMID 32457755, 2020). "In this case, the MHCs class I would carry viral antigens ready to be recognized, but due to the immune escape activated by the tumor cells, with the production of ARG1, LAG3, and CTLA4, they do not recognize it." (PMID 32331228, 2020). "Also, combination therapies may enhance tumor cell immunogenicity while reducing the efficacy of immunosuppressive molecules such as indoleamine 2,3-dioxygenase (IDO), C-X-C Motif chemokine receptor 2 (CXCR2), lymphocyte-activation gene 3 (LAG-3), phosphoinositide 3-kinase (P13K), for example." (PMID 31014381, 2019). "Of note is the fact that LAG-3 is significantly overexpressed in cHL but barely expressed in DLBCL, while PD-L1 is overexpressed by cHL and non-GCB DLBCL, suggesting that these tumor cells are prone to modulating immune activation responses." (PMID 30384489, 2018). "The results showed that there was no significant differential expression of LAG-3, TIM-3, and ICOS on CD8+ T cells between CCL5+/+ and CCL5−/− mice either from tumor or spleen." (PMID 29991744, 2018). "In contrast to LAG-3, cHL and DLBCL exhibit the same level of TIM-3 protein, while both cHL and non-GCB DLBCL tumor cells express TIM-3." (PMID 30384489, 2018). "LAG-3 is an immune checkpoint that binds a non-holomorphic region of the MHC-II molecule and has an important role in the tumor microenvironment." (PMID 28970830, 2017). "In contrast, splenocytes of non-tumor bearing mice contained approximately 2–5% of CD8 and CD4 cells that expressed PD1; and 1–3% that expressed LAG3 (PD1-no tm and LAG3-no tm)." (PMID 26318293, 2015). "CD4 T cells harvested from mice treated with anti-PD-L1 plus anti-LAG-3 or anti-TIM-3 also released IFN-γ when stimulated with 5T33-CIITA cells, but there was no spontaneous or tumor-induced release of IFN-γ, IL-4 and IL-5." (PMID 25614821, 2015). "However, CD8+LAG3+ and CD8+TIM3+ cells were mainly located in the tumor parenchyma of recurrent/metastatic patients, while in non-recurrent/non-metastatic patients, these cells were predominantly found in the stroma." (PMID 40710213, 2025). "Similarly, ZGGS15, an IgG4 BsAb targeting LAG-3 and TIGIT, demonstrated potent anti-tumor efficacy without inducing ADCC, suggesting a safer and more effective approach." (PMID 40567374, 2025). "LAG-3 positivity was significantly correlated with a higher ORR of 70.6% compared to 33.3% in the LAG-3-negative group (P = 0.029), a numerically higher long-term DCR of 88.2% vs. 70.3% (P = 0.271), and a greater mean percentage of tumor shrinkage (−48.7% vs. −23.6%, P = 0.014)." (PMID 39751894, 2025). "Although LAG-3 expression did not correlate with PD-L1 expression in the TCGA-CHOL cohort, this discrepancy could be due to PD-L1's nonspecific expression on both tumor and immune cells, in contrast to LAG-3's specific expression on immune cells." (PMID 39751894, 2025). "Quantitative analysis of PD-L1, LAG-3, and CTLA-4 expression revealed distinct patterns across the tumors, with a relatively uniform abundance of PD-L1 and LAG-3, but absence of CTLA-4 on tumor-infiltrating T cells." (PMID 40674934, 2025). "However, their mAb targets are not tumor-specific considering the broad expression of PD-L1, PD-1, CD20 or LAG3 on healthy cells." (PMID 38338686, 2024). "The approach of fusing IL-15 to mAbs or their fragments has been increasingly pursued in the last years, however, the targets of these next-generation immunocytokines (e.g., PD-1, PD-L1, LAG3, CD20) are not tumor-specific, but rather broadly expressed on healthy cells." (PMID 38338686, 2024). "The anti-LAG3/PD-L1/Paclitaxel treatment showed the most significant metastasis reduction from tumors with NF1, TSC1, or TβRII inactivation but not from the 4T1-C1 control tumor." (PMID 38997291, 2024).
tumor (continued). "However, unlike in the human tumor environment, the human-like CD8 GZMB+ clusters in mouse hardly expressed Lag3 or Klrb1." (PMID 38245530, 2024). "In addition to galectin-3 and LSECtin, fibrinogen-like protein 1 (FGL1) is another important ligand for LAG-3 as a soluble protein that is released by the liver under normal conditions, and FGL1 is highly expressed in a few tumor tissues." (PMID 37055849, 2023). "Despite this, in the 4T1 tumor the increased tumor infiltration by effector T cells did not set the stage for response to anti-PD1 or other antibodies targeting the T cell immunomodulatory receptors GITR, OX40, and LAG3." (PMID 37620372, 2023). "Targeting the co-inhibitory pathways of T cells, termed T cell checkpoints, elicits an antitumor response by shifting the balance from T cell inhibition by co-inhibitory molecules, like LAG-3, PD-1, TIM-3, and CTLA-4, to enhanced pro-inflammatory conditions that no longer support tumor growth." (PMID 37738978, 2023). "Despite being less frequently found in the tumor and ascites, NK cells in tumors displayed significantly increased expression of activating markers such as NK1.1, NKp46, and CD69, but not LAG3 nor NKG2D." (PMID 38235131, 2023). "It will be interesting to investigate whether dual treatment of anti-LAG-3 antibodies which strongly block both MHC-II and FGL1 improves anti-tumour immunity compared to monotherapy, or if there are no benefits from inhibiting both ligands." (PMID 35265944, 2022). "Although baseline LAG-3 and PD-1 levels in tumour samples did not correlate with response, we observed increased frequencies of memory CD4+ and effector CD8+ T cells in the posttreatment tumour specimens of patients with favourable treatment response." (PMID 36289334, 2022). "Elevated serum concentrations of soluble LAG3 are seen in non-responders to anti-PD1 therapy and increased tumor infiltration with T cells positive for LAG3 and TIM3 was also correlated with shorter progression-free survival in patients receiving anti-PD1 immunotherapy." (PMID 35515106, 2022). "In fact, tumor cells were not able to induce proliferation of CD4+ T-cells even when PD-L1 was blocked, which complicates drawing conclusions about the role of the MHC-II/LAG-3 axis in this important T-cell function." (PMID 35655709, 2022). "In addition, while MNK inhibitors did not affect LAG3 expression in tumor-infiltrating CD8+ T cells in both the KPC-344 and the TBP-3868 tumors, MNK inhibitors increased TIM3 levels in tumor-infiltrating CD8+ T cells only in the KPC-344 tumors." (PMID 35380995, 2022). "However, these immunotherapy markers are commonly used in other tumor types (such as PD1 and LAG3), and TMB was not identified as sensitive potential therapeutical target in ccRCC patients." (PMID 35028006, 2022). "There is only one study involved with the relationship between PROZ and immune components based on the Tumor Immune Estimation Resource tool, which found that PROZ has a certain correlation with immune components such as T cells, PD-1, LAG3, TIM3, but there is a lack of histological evidence." (PMID 36140703, 2022). "The upregulation of Ctla4 and Lag3 was rather specific as no significant changes were observed in mRNA levels of Cd80 and Cd86 (two CTLA4 ligands present in the antigen-presenting (tumour) cells), Tim-3/Galectin-9 (Havcr2/Lgals9), and Pd-l1 (Cd274) immune checkpoints." (PMID 36433941, 2022). "This is exemplified by recent observations made in our lab, where LAG-3 blockade alone did not provide a survival advantage to mice bearing 4T1/MC38 tumours, likely due to low tumour immunogenicity resulting in the absence of an immune response requiring regulation." (PMID 35265944, 2022). "Immunomonitoring of bone marrow samples at baseline and during treatment showed a reduction of regulatory T-cell numbers and a decrease in the proportion of T-cells expressing LAG3 and CD8+ T-cells expressing TIM-3, whereas tumor cell characteristics were not affected." (PMID 34070044, 2021).
tumor (continued). "Tumor-infiltrating CD4+ T cells showed significantly elevated expression of PD-1 (NT; 32.5 ± 2.0 vs. TT; 46.3 ± 2.7), TIM-3 (NT; 2.7 ± 0.3 vs. TT; 10.8 ± 1.3) and TIGIT (NT; 26.5 ± 1.8 vs. TT; 37.0 ± 2.1), but not LAG-3." (PMID 33477864, 2021). "In addition, the proportion of CD4+LAG-3+ and CD8+LAG-3+ T cells in MPE after chemotherapy are similar to tumor tissue in one study, but not another." (PMID 33987104, 2021). "At the same time, the expression of PD-1, Lag-3, CTLA-4, Tim-3, and Granzyme B on Tregs from cryo-thermal treated mice was decreased, and the expression of perforin, T-bet and IFN-γ in Tregs was not different from that in Tregs from tumor-bearing control mice." (PMID 34576115, 2021). "In addition, we found that tumor-infiltrating CD25+ T cell express TIM-3 at significantly higher levels than CD25− TILs and also co-express CTLA-4 and PD-1, but do not express LAG-3." (PMID 32041340, 2020). "Tumor-infiltrating immune cells comprise a previously unrecognized diversity of cell types, including CD8+ T cells predominantly expressing the checkpoint marker LAG3, rather than PD1 or CTLA4." (PMID 31980621, 2020). "Nevertheless, such MSI+ CYT-high tumor cells are not effectively eliminated by the immune system, due to the increased levels of several immune-inhibitory checkpoint molecules, such as PD-L1, PD-L2, CTLA-4, LAG3, TIGIT, IDO1 and VISTA." (PMID 31429779, 2019). "Interestingly, CXCL6 and other ARGs also showed negative correlations with checkpoints like VEGFB, KIR2DL1, LAG3, CTLA4, PDCD1, and IFNG, indicating they may promote immune surveillance and anti-tumor responses." (PMID 40943183, 2025). "Accordingly, ADENO showed no LAG-3 expression and therefore might not be a good candidate for extended immunotherapy targeting LAG-3, in contrast to SCC, whereas TIGIT showed similar expression in both tumor entities." (PMID 40647508, 2025). "The tumor-infiltrating immune cells comprised a previously unrecognized subtype of CD8+ T cells that predominantly expressed the checkpoint marker LAG3, rather than PD-1 and CTLA-4, indicating that LAG-3 would be a potential target in immune checkpoint inhibitors in UM patients." (PMID 38966635, 2024). "With our model we were able to obtain good fits if the exhausted state was correlated with HAVCR2 or LAG3 but not with PDCD1/CD274, which was due to the early peak of Pdcd1 and Cd274 transcription that was already well in decline on day 5 while CTL numbers in the tumor remained high." (PMID 37182110, 2023). "Therefore, altogether, these data demonstrate that the simultaneous genetic ablation of PD-1, LAG-3, and TIM-3 expression induced a more sustained anti-tumor activity compared to non-edited T cells resulting in reduced tumor growth as well as increased survival." (PMID 35328630, 2022). "A shift in focus to research and development of novel ICIs which target antigens that are not shared amongst both the myocardium and tumor in question, unlike the current targets PD-1, PD-L1, CTLA-4, and LAG-3 may limit inflammatory reactions against cardiomyocytes." (PMID 36185227, 2022). "PD-1, CTLA4, LAG3, TIGIT, and TIM-3 (HAVCR2) are known as inhibitory molecules expressed in exhausted T cells that have an impaired ability to kill tumors because they neither respond to T cell receptor stimulation nor secrete anti-tumor cytokines such as interferon γ and tumor necrosis factor-α." (PMID 35480109, 2022). "The defect in effector CD4+ T-cell expansion could be restored by B3-Ab:env123–139 immunization of mice bearing established lung metastases, although this alone did not translate to tumor regression or control, and the expanded CD4+ T cells continued to express high levels of PD-1 and LAG3." (PMID 32313208, 2021).